NEMP1 (nuclear envelope integral membrane protein 1)
Description:
Together with EMD, contributes to nuclear envelope stiffness in germ cells. Required for female fertility (By similarity). Essential for normal erythropoiesis (By similarity). Required for efficient nuclear envelope opening and enucleation during the late stages of erythroblast maturation (By similarity).
Synonyms: KIAA0286; TMEM194; TMEM194A
Tractability: Antibody: UniProt predicts a signal peptide or a membrane-spanning region. PROTAC: ubiquitination databases record sites on it.
Gene: Protein-coding gene on chromosome 12 (57,055,643 to 57,088,063, reverse strand). Ensembl gene ENSG00000166881.
Subcellular location: Nucleus inner membrane; Nucleus envelope
Subcellular location (Human Protein Atlas): Nucleoplasm
Gene Ontology:
Biological process: nuclear membrane organization; erythrocyte enucleation; erythrocyte maturation
Cellular component: nuclear envelope; nuclear inner membrane
Genetic constraint (gnomAD): Loss-of-function variants: 19 observed, 40.24 expected, observed/expected ratio (o/e) 0.47, 90% interval 0.33 to 0.69. The upper end of that interval is the gene's LOEUF score, 0.69, which puts it in group 2 of 6, group 1 being the genes least tolerant of losing a copy. Missense variants: 380 observed, 455.26 expected, observed/expected ratio (o/e) 0.83, 90% interval 0.77 to 0.91. Synonymous variants: 163 observed, 169.29 expected, observed/expected ratio (o/e) 0.96, 90% interval 0.85 to 1.1.
Homologues: Orthologues: chimpanzee NEMP1 (99% identical), macaque NEMP1 (97% identical), pig NEMP1 (88% identical), dog NEMP1 (88% identical), rabbit NEMP1 (85% identical), guinea pig NEMP1 (83% identical), mouse Nemp1 (83% identical), rat Nemp1 (83% identical), tropical clawed frog nemp1 (59% identical), zebrafish nemp1 (50% identical), Caenorhabditis elegans nemp-1 (25% identical), Drosophila melanogaster Nemp (23% identical). Paralogues in human: NEMP2 (31% identical).
Diseases named in the same sentence as NEMP1 in open-access papers:
NEMP1 is named in the same sentence as 10 diseases in open-access papers, as found by Europe PMC text mining. Sharing a sentence is not in itself a finding about the gene and the disease. The quoted sentences say what the papers report.
breast carcinoma (4 papers, 2019 to 2023). "NEMP1 is highly expressed in breast cancers and promotes tamoxifen resistance in breast cancer cells in vitro by regulating expression of nuclear receptor coactivator 1 (NCOA1/SRC1)." (PMID 36299481, 2022). "Interestingly, NEMP1 was recently shown as promoting tamoxifen resistance in breast cancer cells." (PMID 31349573, 2019). "The function of NEMP-1/Nemp1 is not known; it has been suggested to have roles in Xenopus neural development, tamoxifen resistance in human breast cancer cells, and to contribute to the stiffness of the nuclear envelope." (PMID 34133414, 2021).
thyroid cancer (4 papers, 2019 to 2022). "This method was validated by stably transfecting two standard human thyroid cancer cell lines (BCPAP and 8505C) with four distinct genes (DDX19B, NEMP1, PANK2, UBALD1) and profiling their transcriptome before and after the transfection." (PMID 33302383, 2020). "Expression data for the GMR Theory validation on thyroid cancer cell lines BCPAP and 8505C were collected from GSE97031 (transfection with NEMP1), GSE97028 (DDX19B), GSE97030 (PANK2) and GSE97427 (UBALD1)." (PMID 31349573, 2019). "Nonetheless, we validated the relationship between the GCH score and the transcriptomic consequences of manipulating the gene expression by stably transfecting DDX19B, NEMP1, PANK2, and UBALD1 on the papillary (BCPAP) and anaplastic (850C) human thyroid cancer cell lines." (PMID 34209090, 2021).
anemia (1 paper, 2022). A reduction in the number of red blood cells, the amount of hemoglobin, and/or the volume of packed red blood cells. "As a consequence, Nemp1 KO mice display anemia and splenomegaly associated with stress erythropoiesis in adult mice." (PMID 36215313, 2022). "Here, we report that Nemp1 KO mice show peripheral blood defects, anemia in neonates, ineffective erythropoiesis, splenomegaly, and stress erythropoiesis." (PMID 36215313, 2022).
female infertility (1 paper, 2022). Diminished or absent ability of a female to achieve conception. "Similarly to the involvement of multiple NE proteins in specific pathologies, Nemp1 deficiency specifically underlies female infertility and erythropoietic defects in mice." (PMID 36215313, 2022).
papillary thyroid cancer (1 paper, 2019). "In our opinion, the strong correlations of the (not yet assigned to a pathway) NEMP1 gene with the oncogenes TFG and HRAS indicate its potential role in the papillary thyroid cancer." (PMID 31349573, 2019).
Splenomegaly (1 paper, 2022). Abnormal increased size of the spleen. "This study shows that genetic loss of the nuclear envelope protein NEMP1 underlies splenomegaly, stress erythropoiesis, and defects of terminal erythropoiesis." (PMID 36215313, 2022). "Even though Nemp1 knockout (KO) mice are overtly normal, they display a pronounced splenomegaly." (PMID 36215313, 2022).
cancer (1 paper, 2020). A tumor composed of atypical neoplastic, often pleomorphic cells that invade other tissues. "Although DDX19B and PANK2 (but not NEMP1 and UBALD1) were synergistically expressed with SPINT2 in PTC, there are no reports relating these genes with SPINT2 in any form of cancer." (PMID 32887258, 2020).
NEMP1 also shares sentences with these, for which no sentence is quoted: asthma (1 paper); schizophrenia (1); tumor (1).